RN7SL141P (RNA, 7SL, cytoplasmic 141, pseudogene)
Gene: Miscellaneous RNA gene on chromosome 3 (172,237,326 to 172,237,591, forward strand). Ensembl gene ENSG00000243398.
Homologues: Orthologues: chimpanzee Metazoa_SRP (93% identical), macaque Metazoa_SRP (88% identical), pig Metazoa_SRP (69% identical). Paralogues in human: RN7SL1 (83% identical), RN7SL2 (83% identical), RN7SL3 (82% identical), RN7SL493P (82% identical), RN7SL220P (81% identical), RN7SL769P (80% identical), RN7SL113P (80% identical), RN7SL122P (80% identical), RN7SL464P (80% identical), RN7SL709P (80% identical), RN7SL804P (80% identical), RN7SL44P (80% identical), and 708 more.